STAT1 (signal transducer and activator of transcription 1)
Diseases named in the same sentence as STAT1 in open-access papers (continued):
Sharing a sentence is not in itself a finding about the gene and the disease.
cancer (continued). "STAT family consists of 7 different subfamilies STAT1, 2, 3, 4, 5a, 5b, and 6, and STAT3 and 5 are constitutively activated in cancer cells." (PMID 23878608, 2013). "To that end, we initiated an interferon response by co-cultivating CAFs and carcinoma cells, leading to the elevation of IFN targets MX1 and STAT1." (PMID 23630584, 2013). "The present work is motivated by the following consideration: We observed differences in the trajectories of the parameterized models describing the IFNγ-induced STAT1 signalling pathway in PSC and cancer cells." (PMID 23284277, 2012). "EP300, ISGF3G, STAT1, and STAT3 are up regulated in 8/13 of cancer models, while ATM, BAX, BCL2L11, HTATIP2, LGALS3, MAPK1, and TP73L are down regulated in half of cancer models." (PMID 19402918, 2009). "Beyond AKT, USP12 also stimulates STAT1 signaling and USP46 regulates the cell cycle through stabilizing the CRL4Cdt2 E3 ubiquitin ligase complex, which promotes proliferation of HPV-transformed cancers." (PMID 41533576, 2026). "Correlation analyses confirmed a strong correlation between PD-1 and its ligands, whereas STAT1 and STAT3 expression showed no direct association with PD-L1 or PD-L2 levels in cancer samples." (PMID 42279246, 2026). "Additionally, bafilomycin decreased HER2 surface expression, impairing trastuzumab binding, and modulated immune regulators (STAT1, CD95, and PD-L1) in NK and/or in the cancer cells." (PMID 40650051, 2025). "Still, controversy exists in this field, with reports indicating both positive and negative correlations between STAT1 expression and cancer progression." (PMID 41367865, 2025). "Topoisomerase inhibitors increase ROS levels in the cell, which leads to the activation of Janus tyrosine kinase 2 (JAK2)-signal transducer and activator of transcription 1 (STAT1) and thus elevated CXCL1 expression, as shown in experiments on many types of cancer." (PMID 40427171, 2025). "Notably, cancer cell-derived type III collagen autonomously triggers DDR1 activation, which subsequently enhances STAT1 expression." (PMID 40563472, 2025). "Of interest, the expression patterns of STAT1 and STAT2 were variable in various cancer types." (PMID 38191598, 2024). "Besides STAT1 and STAT2, other components of the JAK/STAT pathway have been studied in the pathogenesis of cancer, including STAT3." (PMID 39405604, 2024). "Additionally, STAT1 and STAT6 also play a role in metabolism as STAT1, STAT3, STAT5, and STAT6 each play a role in the creation of a dynamic metabolism within cancer cells." (PMID 38464736, 2024). "Meanwhile, we found that MgIG and GA protected against hepatotoxicity to counteract ferroptosis without affecting or compromising the anti-cancer activity of Crizotinib, with a mechanism potentially related to the Stat1/Nrf2 pathway." (PMID 39160159, 2024). "To explore the potential of utilizing STAT1-mediated activated GAS-NK cells, we investigated whether activation could be induced through co-culture with cancer cells." (PMID 39349746, 2024). "Clinically, p-NF-κB, p-STAT1, and IRF1 expressions were examined in benign and cancer tissue." (PMID 38540186, 2024). "In addition, IFN-λ acted together with related genes such as STAT1, STAT2, and STAT3 affecting the JAK-STAT signaling pathway to promote cancer progression." (PMID 37697300, 2023). "Transcription factor (TF) motifs, including CEBPB (+), FOSB (+), SAP30 (+) and ATF4 (+), were significantly upregulated in CNV high cancer cells, while IRF3 (+), ETV7 (+), STAT1 (+) and IRF7 (+) were downregulated, indicating promising new regulatory networks driven by TFs in OS cells." (PMID 36596773, 2023). "Moreover, STAT1 and STAT3 were shown to be generally high-expressed in pan-cancer myeloid cells, and STATs all had positive correlation with the infiltration of the majority of immune cells." (PMID 36968603, 2023).
cancer (continued). "A time course study with IL-10-neutralized MDSCs supernatant on Dox resistant cancer cells, showed downregulated p-STAT3 expression as early as 60 mins post treatment, whereas, IL-6- neutralized supernatant has showed decreased p-STAT1 activation after 240 mins of treatment." (PMID 38304256, 2023). "A study found that one of the mechanisms of cetuximab is through the induction of the IFN/STAT1 signaling pathway, which promotes cancer survival rather than inhibition in tumor cells." (PMID 36765706, 2023). "Moreover, PRs can interact with STAT1 to inhibit IFN-induced STAT1 phosphorylation, thereby inhibiting carcinoma development." (PMID 37483519, 2023). "In addition, highly expressed STAT1, a target PCG of miR-944, can serve as a biomarker for poor clinicopathological features and poor prognosis in cancer patients." (PMID 36077769, 2022). "We identified an increase in phosphorylation of P65 and Smad2/3 in platelet-exposed cancer cells but did not detect a significant increase in phosphorylation of STAT1/3." (PMID 35626102, 2022). "Our results demonstrate that MUC1-C in a complex with STAT1 and IRF1 constitutively activates ISG15 transcription, in support of MUC1-C involvement in integrating chronic activation of the type I IFN pathway with induction of ISG15 expression in cancer cells." (PMID 35681561, 2022). "Other known and possibly yet undiscovered cancer mechanisms are captured by the SKY92, including cell cycle pathways (BIRC5, TOP2A, and CENPE), cell growth and proliferation (FGFR3), DNA repair (FANCF, FANCI, POLQ), and transcription factor (STAT1)." (PMID 34448362, 2022). "In contrast, expression of Stat1 was increased in cancer cells of Tyk2ΔIEC tumors while expression of Stat3 and activation of Stat1 and Stat3 were not altered." (PMID 36185806, 2022). "High-LPCAT1 expression could inhibit STAT1 expression, up-regulate CyclinD1, CyclinE, CDK4 and MMP-9, and decrease p27kip1 to promote cancer progression in HCC." (PMID 36307879, 2022). "Considering C‐MAF’s involvement in cancer development and potential regulation by STAT1, this SNP may prevent C‐MAF binding upstream of STAT1." (PMID 35739459, 2022). "In addition, STAT1 and STAT3 are involved in PD-L1 expression and PD-1 checkpoint pathway in cancer by pathway analysis." (PMID 35874683, 2022). "This speculation was preliminarily supported by the significant correlations between STAT1 and MDK in various cancers in the TCGA database." (PMID 35747815, 2022). "The aberrant activation of STAT proteins, most particularly STAT1, STAT3 and STAT5, has been suspected or proposed to significantly contribute to the progression of a variety of human tumors and cancer cell lines, including hematologic malignancies and solid tumors." (PMID 35163491, 2022). "Furthermore, deactivation of the key signaling pathways involved in cancer progression such as NF-κB, ERK1/2, p38, STAT1, STAT3, STAT5 was also evaluated by this technique." (PMID 36230847, 2022). "To date, a direct link between primary cilia and STAT1 or DR5 signaling in cancer has not been reported." (PMID 36127323, 2022). "Indeed, we detected increased STAT1 expression and activation, but decreased p-STAT3 levels in miR-155–overexpressing cancer cells." (PMID 35925680, 2022). "Similarly, the altered frequencies of STAT1 and IFIT3 came second and fourth among 525 samples from the pan-cancer TCGA cohort." (PMID 36311733, 2022). "Indeed, the authors found an increased level of STAT1 in cancer cells with HER2 downregulation, whereas inhibition of STAT1 with fludarabine blocked the immune-related HER2 downregulation." (PMID 36627895, 2022). "In the carcinoma cells of gall bladder, the activation of STAT1 was significantly found in comparison to the nonneoplastic carcinoma cells." (PMID 35035811, 2022).
cancer (continued). "An overview of different strategies adopted to suppress these IRDS genes (for example; STAT1, IRF7, OAS family and BST2) in cancer inducing the sensitivity (chemo- and radiotherapy), as well as different ways by which the viruses inhibit the IRDS genes are addressed in this review." (PMID 33922087, 2021). "Furthermore, cancer cell exosomes can transmit αvβ6 to monocytes, promote M2 polarization, and then inactivate the STAT1-MX1/2 pathway, of which STAT1 is vital for tumorigenesis and development." (PMID 34485600, 2021). "IFN-γ can also mediate cancer cell dormancy in a STAT1-independent way and the effects of IFN-γ might be partly dependent on the properties of the cancer cells." (PMID 33771156, 2021). "On the other hand, STAT1, found down-regulated in the same cell lines, as opposed to STAT3, elicits pro-apoptotic and anti-proliferative responses and promotes anti-cancer immunity." (PMID 33898418, 2021). "Our in silico analysis using TCGA cohort revealed correlations between IRF1 and STAT1 or STAT2 mRNA in HNSCC and LUAD, suggesting that STAT1 and/or STAT2 may be mainly involved in PD-L1 expression in these cancers." (PMID 34069326, 2021). "Besides, due to the notion that STAT1 and STAT3 play opposite role in cancer-relevant processes, we also evaluated the expression of STAT3 in our experimental models." (PMID 34642300, 2021). "High levels of LpCat1 in HCC could inhibit STAT1 expression, up-regulate CyclinD1, CyclinE, CDK4 and MMP-9, and decrease p27kip1 to promote cancer progression." (PMID 34178664, 2021). "Therefore, it would be interesting to investigate the role of STAT1 and STAT2 as well as KPNA1 in radiation-increased KPNB1-mediated IRF1 expression in these cancers." (PMID 34069326, 2021). "Elevated STAT1 expression correlates with prolonged cancer-specific survival in patients with localized PCa, while no STAT1 expression in patients with advanced PCa is accompanied by early biochemical recurrence." (PMID 34638338, 2021). "In addition, STAT1 and STAT3 have different roles in cell apoptosis and the progression of malignant tumors." (PMID 33361763, 2020). "For this, we implanted either Stat1-positive or Stat1-negative RT2-cancer cells into syngeneic mice." (PMID 32165639, 2020). "In contrast, ICB did not arrest Stat1-negative RT2-cancers that grew rapidly even when treated with ICB." (PMID 32165639, 2020). "Most Stat1-positive and Stat1-negative RT2-cancers (>80%) were rejected." (PMID 32165639, 2020). "In patients with cancer, a positive or negative prognostic value has been correlated to the activation state of STAT1 and NF-κB pathways, respectively, despite the signaling of either being enough to lead to PD-L1 expression." (PMID 33324403, 2020). "RT2.Stat1+/+-cancer cells and RT2.Stat1−/−-cancer cells expressed normal levels of Tag, the antigen targeted by the immune therapy." (PMID 32165639, 2020). "Clearly, markers, such as STAT1, that further subgroup MSI cancers would be beneficial." (PMID 32275681, 2020). "Taken together, miR-584 may have an unvalidated cancer-related targetome that includes PTEN, CCND1, PIK3CA and STAT1." (PMID 32615958, 2020). "In cancer cells, STAT1 and STAT3 may interfere with each other, and perturbation of the balance of STAT1 and STAT3 levels is suggested as a novel therapeutic strategy for cancers." (PMID 30956773, 2019). "Remarkably, STAT1, which has been intensively reported by numerous studies to be downregulated by hrHPV oncogenes, is strongly upregulated not only in CESC but also in the majority of cancer types listed here." (PMID 30918060, 2019).
cancer (continued). "Of these, the average expression of the two genes, including CD70 and PDCD1, and the 12 isoforms derived from the seven genes, including CD40, CD70, IL6, IL10, STAT1, STAT6, and TNFRSF14, were cancer immunotherapy-related genes (false discovery rate (FDR) < 0.01)." (PMID 31292525, 2019). "The tissues from borderline as well as malignant tumors showed significantly elevated levels of STAT1 as well as pSTAT1-Y701, and pSTAT1-S727 compared to the normal ovarian tissue." (PMID 29751820, 2018). "STAT1 is a transcriptional factor which mediates responses to all types of IFNs and regulates a variety of cellular activities, whereas the impairment of TGF-β signaling has been found in various diseases, including cancer." (PMID 29751820, 2018). "Based on our result, IFNγ might be an effective anti-cancer drug for tumors that lack a high level of expression and/or activation of ERK, and/or express a certain basal level of STAT1 that can be activated." (PMID 29855346, 2018). "As IFN-γR is also expressed in cancer and directly connected to the same first neighbours (JAK1 and STAT1) as the cancer-related IL10R, IFN-γR may substitute the role of IL10R upon IFN-γ treatment." (PMID 28603644, 2017). "Although STAT1 has been regarded as a tumor suppressor protein with some functions that oppose the tumorigenic role of STAT3, it can substitute for STAT3 in certain cancer cell lines and adopt a pro-tumorigenic role." (PMID 28636670, 2017). "While the involvement of ERK mediated the expression and activation of STAT1 has not been previously reported in human cancer models." (PMID 28431406, 2017). "SEL120-34A inhibits phosphorylation of STAT1 S727 and STAT5 S726 in cancer cells in vitro." (PMID 28422713, 2017). "Hit compounds were confirmed in dose response experiments and further analyzed for their ability to inhibit STAT3 phosphorylation, downregulate STAT3- and STAT1-driven gene expression, and for their potential to impair the viability in STAT3-dependent and -independent cancer cell lines." (PMID 28636670, 2017). "The competitive pull-down assay with Bio-BENDA that was newly designed and synthesized to investigate the interaction between BENDA and cellular STAT3 indicated that BENDA tightly bound to STAT3 but not STAT1 in cancer cells." (PMID 28125678, 2017). "On the other hand, ONA also slightly inhibited STAT1 and STAT5 activation, thus suggesting that the other pathways besides STAT3 also might contribute to the anti-cancer therapeutic effects of ONA." (PMID 27404320, 2016). "It should be noted that, in contrast to STAT1/2/5 proteins, constitutive and IL-6-induced STAT3 phosphorylation was shown to be reduced upon treatment by SFN in a number of cancer cell lines, thus revealing multiple modes of regulation of STAT proteins by ITCs." (PMID 27304884, 2016). "Interestingly, STAT1[Gene ID: 6772], NFKB1[Gene ID: 4790] and JUN[Gene ID: 3725] genes, three crucial signaling molecules in cancer cells, have been further identified as common targets of the three compounds." (PMID 26359356, 2015). "Taken together, these results demonstrate that EF24 selectively blocks the NF-κB pathway in cancer cells, but does not affect STAT1 or STAT3 activation." (PMID 23940701, 2013). "Our results therefore allow the conclusion that the differences in IFNγ induced nuclear accumulation of STAT1 are not restricted to the two originally used cell lines but reflect a general difference between pancreatic stellate and cancer cells." (PMID 23284277, 2012). "Gene ontology, molecular network and canonical pathway analysis of NASP overexpression demonstrated that the most significant changes were in proteins participating in organismal injury, immune response, and cellular growth and cancer pathways (major "hubs": TNF, FOS, EGR1, NFκB, IRF7, STAT1, IL6)." (PMID 19439102, 2009). "Finally, we examined whether STAT1 and UCP2 expression could have prognostic value for cancer patients." (PMID 41367865, 2025).
cancer (continued). "However, chronic activation of MUC1-C→STING/STAT1 signaling in NSCLC and other cancer cells could constitute an irrevocable response that drives genomic instability and drug-resistant cancer progression." (PMID 40781226, 2025). "We made use of the EGFRmut NSCLC persister model PC9, which has tunable low or high STAT1 pathway activity in the absence or presence (respectively) of IFNγ stimulation and was used in the initial discovery of the type I PRMT vulnerability in persistent cancer cells." (PMID 39699269, 2025). "However, our data also shows that in cancer patients, STAT1 levels do not correlate with clinical parameters." (PMID 41367865, 2025). "We found a significantly higher expression of STAT1 in cancer; however, the counts in non-neoplastic tissue were relatively high, and with 12% of the patients having threefold expression of STAT3 in cancer, the difference between cancer and non-neoplastic tissue was modest." (PMID 38979413, 2024). "Yet, a direct role for USP18 in transcription regulation has not been reported, but it might form a complex with STAT2/STAT1/IRF9 to enhance expression of ISGs in cancer cells." (PMID 37002195, 2023). "The balancing act between pro-survival STAT3 signaling and pro-death STAT1 signaling downstream of cGAS/STING signaling resulting from CIN allows cancer cells to cope when the insult is not too severe, while still allowing cells to induce apoptosis and promote immune clearance when needed." (PMID 37561163, 2023). "IFN-γ-induced p-STAT1 was diminished in B cells, but not T and NK cells, from all cancer groups." (PMID 37741983, 2023). "Combining pseudotime, RNA velocity–PAGA, cellular entropy, and regulon analysis in stromal cells reveals a cancer-specific rewiring of fibroblasts, where STAT1, TGF-β, and inflammatory signals induce a noncanonical WNT5A program that maintains the stromal inflammatory state." (PMID 35687691, 2022). "Previous studies showed that treatment with RIG-I agonist resulted in the activation of proinflammatory transcription factors STAT1 and NF-κB and increased expression of MHC-I components in cancer cells, Therefore, DDX60 may serve as a signaling transductor to activate the RIG-I pathway." (PMID 36551849, 2022). "Although the exact mechanism for the relationship between increased tumorigenesis and IFN signaling in ER+ tumors is not yet clear, there is evidence that STAT1 and ER signaling may synergize for enhanced cancer cell proliferation." (PMID 35132960, 2022). "While NF-κB and TGFβR1/Smad signaling played a role in platelet-induced PD-L1 expression, we could not find any significant change in phosphorylation of STAT-1 or STAT-3 in platelet-exposed cancer cells." (PMID 35626102, 2022). "Collectively, our data identify a novel IFN-γ-STAT1-MDK signalling axis, which confers the pro-metastatic adverse effect of IFN-γ in immunotherapy, whereas targeting MDK may efficiently abrogate IFN-γ-elicited cancer metastasis." (PMID 35747815, 2022). "To gather information about p300 and CBP in human cancer, we examined The Cancer Genome Atlas (TCGA) dataset and found significant correlations between EP300 or CBP mRNAs and genes identified by our integrative RNA-seq and ATAC-seq analyses, including RELA, STAT1, NFKB1, IFNGR2, and NLRC5." (PMID 33602823, 2021). "Besides, many cancers develop unresponsiveness to IFN-I in order to overcome its cytostatic effects by downmodulating its receptor chains, upregulating the negative regulators of the JAK-STAT pathway such as SOCS1, or reducing the expression of STAT1." (PMID 33671123, 2021). "The variable associations between survival and STAT1 expression may have arisen because the function of STAT1 has been analyzed in the early and late stages of cancer, without taking into consideration that the effects of this molecule may be stage-dependent." (PMID 34299314, 2021).